CD4 (CD4 molecule)
Diseases named in the same sentence as CD4 in open-access papers (continued):
Sharing a sentence is not in itself a finding about the gene and the disease.
tumor (continued). "This correlated with a pronounced increase in CD4+ICOS+ T cells in peripheral blood, as well as a clear increase in proliferating CD4+ T cells as determined by Ki-67 staining, although we did not detect this increase in the tumor as well." (PMID 23626745, 2013). "Furthermore, subsequent study revealed that nontumor LCs cultured in the presence of tumor supernatant (TSN) demonstrate an enhanced proliferation of both CD8+ and CD4+ T cells, with a shift towards a Th1 and CD8+ T cell response." (PMID 23606870, 2013). "Interestingly, radiation therapy significantly increased proliferation of CD8 T cells and non-regulatory CD4 T cells as measured by expression of Ki67, suggesting that endogenous immune responses may be more active in the spleen following radiation therapy of the primary tumor." (PMID 23936036, 2013). "PEC fractions from tumor-bearing WT and p47phox−/−mice were co-cultured with anti-CD3/B7.1-stimulated CFSE-loaded splenocytes from non-tumor-bearing WT mice (E∶T ratio 1∶1), and CD4+ and CD8+ T cell proliferation was assessed by CFSE dye dilution." (PMID 23922763, 2013). "However, the expression of IL-10 and infiltration of T lymphocytes (e.g., CD3+, CD4+, CD8+) as well as their correlation within tumor tissues are not known, which needs further investigation." (PMID 24116074, 2013). "In our study, inhibition of tumor growth by MB-FUS was accompanied by a significant increase in the percentage of non-Treg CD4+ and CD8+T cells and an increase in the ratio of CD8+/Treg, suggesting that changes in these cell populations within the tumor microenvironment indeed affected tumor growth." (PMID 23140567, 2012). "In this regard, statistical comparison between the no tumor, low and high tumor burden group revealed significant differences for CD69+ CD4+ lymphocytes in spleens and for both CD25+ CD8+ and CD69+/CD25+ CD4+ lymphocytes in ndLN (all p < 0.05; Kruskal–Wallis test)." (PMID 22674057, 2012). "In addition, both CD4+ and CD8+ T cell counts were lower in CT26/luc tumor-bearing mice (never), but not in the mirtazapine-treated, tumor-bearing mice (always, concurrent, and after) as compared with those of wild type and drug." (PMID 22808019, 2012). "In addition, IL-10 inhibits secretion of the proinflammatory cytokines by CD4+ T cells and impairs CD8+ T cells response, whereas tumor clearance can be enhanced in the absence of IL-10." (PMID 23176085, 2012). "Similarly, percentages (data not shown) and absolute numbers of CD4+ and CD8+ T cells were significantly increased in local lymph nodes and spleens in ST2−/− mice compared with tumor-bearing WT mice (p<0.05)." (PMID 21484786, 2011). "Furthermore, in contrast to anti-CD4, anti-CD25 treatment did not induce detectable priming of TRP-2 specific CD8 T cells in tumor-bearing mice." (PMID 22046294, 2011). "Preliminary experiments showed that supernatants from tumours treated with any of the drugs had no direct effect on the numbers and/or activation states of NKs (CD3−, CD69+, CD56+ and CD16+), T cells (CD3+, CD25+ and CD69+) and T-regs (CD4+, CD25+ and Foxp3+)." (PMID 19997099, 2010). "While tumor bearing mice demonstrated decreased levels of miR-17-92 in both CD4+ and CD8+ cells, human GBM patients exhibited a statistically significant decrease of miR-17-92 in CD4+ cells but not in CD8+ cells." (PMID 20167088, 2010). "They observed a 10-fold increase in the numbers of specific T cells and demonstrated that GITR signaling directly acted on CD8+ T cells, and, in a CMS5 sarcoma model, GITRL inhibited tumor growth which was dependent on the presence of CD8+, but not CD4+ T cells." (PMID 20936139, 2010). "Due to the decrease in CD4+ cells, BCG may not be able to sufficiently stimulate the host immune system to create the necessary anti-tumor activity in the HIV-infected patient." (PMID 19719844, 2009).
tumor (continued). "At 2 weeks after tumour implantation, CD8+, but not CD4+, T cells in tumours treated with MJ18 were significantly more than that in controls, as indicated by real-time PCR (CD8+ T cells, n=3, P=0.024; CD4+ T cells, n=3, N.S.; controls, n=4)." (PMID 19844235, 2009). "Moreover, percent CD4+ cell apoptosis was positively correlated (r = 0.964) with the PGE2 level of individual supernatant, whereas theaflavin-pre-treated tumor supernatants failed to induce significant death." (PMID 19812686, 2009). "Recent reports suggested that thymic-derived CD4+CD25+ regulatory T cells (Treg; Foxp3+ lymphocytes) participate in the control of tumour immunity, but whether Treg control tumour immunity in OSCC has not been established." (PMID 18349839, 2008). "Although most tumour cells do not express MHC class II molecules, CD4+ T cells can effect an antitumour response in the absence of CD8+ T cells by secreting cytokines, such as interferon-γ, or by activation and recruitment of effector cells such as macrophages and eosinophils." (PMID 16421594, 2006). "Since no specific CD4+ or CD8+ T cells generated by the exosome vaccines could be detected and could account for the tumor regression in patient#12, what could have been the primary effectors accounting for antigen spreading?" (PMID 15740633, 2005). "In addition to granulocytes, a small number of CD4+, CD8+, or NK cells were found near/around the tumours, but the pattern of these cells was not affected by Fas-Lribozyme indicating that infiltration of these immune cells involved other chemotatic signal." (PMID 12177809, 2002). "Flow cytometry analysis of splenic T cells from CT2A tumor–bearing mice demonstrated that treatment with cilengitide, AR-A014418, or WP1066 increased the populations of CD3+ (CD45+CD3+) and CD8+ (CD45+CD3+CD8+CD4–) T cells, but not CD4+ (CD45+CD3+CD4+CD8–) T cells." (PMID 40131864, 2025). "Similarly, as first-line treatment for advanced NSCLC, the combination of the personalized neoantigen vaccine NEO-PV-01 with pemetrexed, carboplatin, and pembrolizumab induced neoantigen-specific CD4+ and CD8+ T cell anti-tumor responses without treatment-related serious adverse events." (PMID 40563603, 2025). "However, we did not distinguish among CD4+ T cell subsets—such as Th1, Th2, Th17, or FOXP3+ regulatory T cells (Tregs)—each of which can exert distinct and sometimes opposing immunologic effects within the tumor microenvironment." (PMID 40805225, 2025). "Therefore, low levels of IL-2 at baseline may result in the preferential expansion of long-lived memory CD4 + T cells but not CD8 + cytotoxic T-cell populations, thus potentially having an impact on anti-tumor activity and OS." (PMID 39984775, 2025). "Moreover, age-related shifts within CD4+ and CD8+ T-cell subpopulations may influence total counts without necessarily indicating improved anti-tumor immunity." (PMID 40791238, 2025). "In contrast to interference with the recall of preexisting CD8+ T cells, VZV-vax-specific CD4+ T cells did not appear to be impeded by preexisting antibodies, as IT injection of the gE-based VZV vaccine led to efficient recall of CD4+ T cell responses and at least partial tumor control." (PMID 40280970, 2025). "Thus, both current and previous findings suggest that the status of CD4‐positive T cells, rather than the number of CD8‐positive T cells, around the tumor cells may influence the therapeutic effect of BCG." (PMID 40084633, 2025). "However, it is also notable that a series of genes that are expressed in activated CD8+ T cells (Gzmb, Prf1, Il2, Ifng, Tnf, Fasl) or in activated CD4+ T cells (Tgfb1, Cd40lg, Il2, Ifng, Tnf, Fasl) were not upregulated in the relevant CD8+ and CD4+ clusters in tumours versus normal." (PMID 40473819, 2025).
tumor (continued). "Additionally, mice receiving SDT+anti-PD-L1 therapy to their primary tumour have been observed to have significantly higher levels of infiltrating CD4+ and CD8 + T-cells in any residual off-target tumour tissue, compared to those who did not receive SDT+anti-PD-L1 therapy." (PMID 39537767, 2025). "However, it should be noted that knockdown of SEMA7A did not influence the percentages and absolute numbers of CD4+T, CD8+T and Treg cells in the TME of tumor-bearing mice, suggesting that macrophages might be the main target cells of SEMA7A." (PMID 41019072, 2025). "There was a significant increase in CD8+ and CD68 + T-cell infiltration from baseline tumor samples to day 5 of treatment (CD8: Wilcoxon signed-rank test V = 57, P = 0.032, n = 11, CD68: Wilcoxon signed-rank test V = 56, P = 0.042, n = 11), but not of CD4+ cells." (PMID 38216554, 2024). "Despite the strong predictive power of our p-Signature, ssGSEA analysis showed that a negative correlation between p-Signature and activated CD4+ and CD8+ T cells, suggesting that higher level p-Signature score may indicate an immune-evasion tumor immune microenvironment." (PMID 39161762, 2024). "We found that treatment of DKO with the anti-VISTA antibody resulted in a significant reduction in the tumor size/tumor weight but increased in spleen weight and frequency of CD8+ T cells without any change in the frequency of CD4+ T cells, NK cells and CD11b+ cells." (PMID 38668817, 2024). "To examine the relationship of intestinal and tumor-infiltrating T cells in SFB-colonized and non-colonized mice with B16-3340 tumors, we performed single-cell RNA sequencing and TCR repertoire analysis (scRNA-seq + scTCR-seq) with sorted CD4+ T cells from these tissues." (PMID 39185202, 2024). "In the present study, we did not investigate whether the CD4/CD8 TIL and FOXP3 levels in the tumor specimens correlated with VEGFR2 expression, and the biological mechanism underlying the increased efficacy of RD after continuous ICI treatment for >180 days remains unresolved." (PMID 38013668, 2024). "To assess the impact of XL413 plus Olaparib treatment on the tumor microenvironment, we analyzed the tumor‐infiltrating immune cells and found that the combination treatment significantly increased the percentage of tumor‐infiltrating CD8+ T cells, but not that of CD4+ T cells or B cells." (PMID 39412086, 2024). "Consistent with our RNAseq findings, tumor imaging (mIF) results on-treatment demonstrate that, in addition to an increase in tumoral CD8 T cells, tumors classified as CD8 converters also had a significantly higher frequency of macrophages and CD4 T cells compared to non-converters on-treatment." (PMID 39190534, 2024). "However, a recent study reported that the immune classification of EC based on tumor infiltrating CD8+ T cells, CD4+ T cells, Tregs, B cells, and plasma cells could not predict patient survival." (PMID 38017652, 2024). "In addition, flowcytometry analysis of tumor infiltrating immune cells showed that mPRMT1 restored the increased immune suppressive CD11b+Gr1+MDSC and reduced CD8+ T cells of mRIP3 tumors, but not affecting the ratio of CD4+ T cells." (PMID 37005412, 2023). "Besides, no direct relationship of CD4 + CXCR5 protein expression with patients’ age, gender, tumor location, tumor diameter, degree of differentiation, TNM stage, presence/absence of signet-ring cells, and presence/absence of neural and vascular invasion (all P > 0.05)." (PMID 36859111, 2023). "In contrast, T/P-induced senescence led to increased CD4+ and CD8+ T cells in nearly all tumors regardless of the resident organ, though the infiltrating T cells were not activated and T cell depletion studies indicated they did not contribute to anti-tumor immunity in the lung or pancreas TME." (PMID 37142692, 2023).
tumor (continued). "We also found that the expression levels of TIGIT on CD8 + T cells, CD4 + T cells and NK cells in TILs and TDLNs treated with RT were statistically significantly higher than expression levels on cells not treated with RT in LLC and B16 tumor-bearing mouse models." (PMID 35794399, 2023). "Overall, our study highlights the selectivity of direct presentation of endogenous antigens by MHC-II+ tumor cells and demonstrates that neither CIITA expression nor the presence of a membrane-bound antigen is sufficient alone to promote direct recognition of tumor cells by CD4+ T cells." (PMID 36512410, 2023). "Flow cytometric analysis of MC38 tumor-infiltrating immune cells showed an increased accumulation of CD8+ T cells, but not CD4+ T cells, NK1.1+, or CD19+ cells in the Rig-I–/– mice compared with their WT littermates, which was verified by IHC analysis of tumor-infiltrating T cells." (PMID 36927693, 2023). "Tumor immune infiltration analysis by CIBERSORT showed a significant correlation between PZP expression and several immune cell infiltrations, and IHC further confirmed a positive correlation with CD4+ T-cell infiltration and a negative correlation with CD68+ M0 macrophage infiltration." (PMID 37509617, 2023). "It is clear that 4-1BB expression is often confined to a small subset of tumor-resident T cells (most often less than 20%), and many of these can be Treg, or it is only seen in certain tumor types and not others, while most conventional CD8 and CD4 T cells within tumors may lack 4-1BB." (PMID 37662949, 2023). "In addition, another study showed that following melanoma-specific CD4+ T cell therapy combined with OX40 co-stimulation or anti-CTLA-4, complete tumour eradication was dependent on neutrophils killing of antigen-negative tumour cells." (PMID 37180120, 2023). "While an exact role of CD49c/CD29 interaction with galectin-3 is not described in human CD4 and CD8 αβ T cells, these interaction partners are responsible for the failure of Vδ2 T-cell proliferation in the presence of galectin-3 producing cells such as tumor cells." (PMID 38259448, 2023). "They promote non-regulatory CD4 + and CD8 + T cell survival, maintain anti-apoptotic proteins BCL-XL, BCL-2 and BFL1 expression, increase cytokine production, enhance tumor-specific T cell immune responses, and increase tumor-specific memory T cell production after antigen challenge." (PMID 37462769, 2023). "Tumor infiltrate was mainly characterized by CD4+ T cells, and the average number of CD4+ T cells was 16-fold higher in GL261 tumors in pre-vaccinated mice as compared to GL261 tumors in non-vaccinated mice (CD4+: 2,622 cells/mm2 in challenged GL261; CD4+: 153 cells/mm2 in GL261)." (PMID 36993983, 2023). "Control CD4+ T-cells cultured the same way, but without peptides, produced low amounts of IFN-γ, granulysin and granzyme B and displayed poor cytotoxic activity against MHC-II-positive Capan-1 cells, which shows that the peptide-specific T cells were recognizing the tumor cells in a specific manner." (PMID 35655709, 2022). "The elevated, tumor-specific response of CD4+ and CD8+ T cells in HCC patients following ablation and the spontaneous regression of untreated (distant) as well as ablated primary tumors in animal models suggest that ablation elicits a systemic, albeit not curative, anti-tumor response." (PMID 36293298, 2022). "The tumor-infiltrating CD8+ T cell expression level in RGC was significantly higher following benign initial disease than following malignant initial disease (p=0.046), whereas the tumor-infiltrating expression of CD8, CD4, FoxP3, and CD20 was not directly relevance with RFS." (PMID 36451224, 2022). "Furthermore, these areas also showed little to no expression of markers associated with inflammatory or interferon signaling (including CD45, CD3, CD8, CD4, and PD-L1), indicating that the T cells derived from the infusion product detected by TCR sequencing were not present within the tumor bed." (PMID 35264439, 2022).
tumor (continued). "A detailed analysis of the T-cell populations revealed a significant decrease in both the CD4+ T-helper cells and CD8+ cytotoxic T-cells in the tumour-bearing SID animals compared to the tumour-bearing animals without operations as well as the tumour-free control animals." (PMID 36010845, 2022). "IL17A, although not changing overall GvHD and graft versus tumor (GVT) activity, contributes to the early development of CD4‐mediated GvHD by promoting the production of proinflammatory cytokines and might have contributed to the bodyweight loss in the early phase after aGvHD induction." (PMID 36051085, 2022). "Additionally, the fraction of intratumoral CD8+ and CD4+ T cells was higher in CTX + ICB + CXB-treated mice compared with CTX + ICB- or control-treated mice, with no clear difference in their number per gram of tumor across any of the groups." (PMID 35440553, 2022). "Moreover, strong negative correlations were found between frequencies of FoxP3-Helios- non-Tregs and CD4+TIM-3+ T cells in TILs, and they were found to be stronger in advanced tumor stages compared to early stages (r = −0.751, p = 0.019 [early]; r = −0.812, p = 0.0007 [advanced])." (PMID 36146549, 2022). "Immunohistochemically, the staining results of tumor cells in the small intestine and kidney were consistent; the tumor cells were positive for CD3, CD56, granzyme B, TIA-1, and perforin, while negative for CD4, CD8, CD5, Desmin, CD34, CKpan, CD20, CD30, SMA, CD79ɑ, and PAX8." (PMID 36199094, 2022). "Third, other immune cells, such as CD4+, CD163+, PD-1+, and PD-L1+ TILs, were not evaluated in the present study, which could be helpful for a comprehensive understanding of the relationship between systemic inflammation and the tumor microenvironment." (PMID 35915403, 2022). "CD4+ T cells can bind to the non-polypeptide domain of MHC class II molecules, take part in T cell antigen receptor (TCR) signal transduction, and then initiate the differentiation of CD8+ T cells into cytotoxic T lymphocytes (CTL), maintaining and enhancing CTL’s anti-tumor response." (PMID 36230580, 2022). "Notably, primarily resected tumors are not the ideal control for comparison with more advanced tumors from patients who receive NEO, potentially explaining why there was no observable difference in the percentage of tumor-infiltrating CD8+ and CD4+ T cells between the PR and NEO cohort." (PMID 36509285, 2022). "Transfer of a small number of CD4 T cells into lymphopenic mice, in combination with CTLA-4 blockade or CD137 agonist immunotherapy, resulted in potent rejection of large vascularized tumours, independent of other immune cells and in an MHCII-restricted manner." (PMID 35572552, 2022). "In contrast, tumor-reactive CD4+ TILs were primarily represented by the CD137- Antitumor function+ (average 69%) and CD137+ Antitumor function+ (average 26%) populations, indicating that CD137 is critical for identifying the CD8+ but not the CD4+ reactive TIL repertoire." (PMID 34707600, 2021). "Interestingly, at 8 days post cryoablation, frequencies of CD4+ conventional T-cells and their proliferation status were significantly increased in both the TDLN and the contralateral tumor non-draining lymph node (TNDLN) only in the fast freeze group, indicative of systemic immune responses." (PMID 34149738, 2021). "They found common transcriptional pathways that were upregulated in the tumor, stroma, and CD4 T cell populations of ERG negative patient tumors, including the PD-1 and IFNγ signaling pathway, suggesting that ERG tumor cells may give rise to a distinct immune cell niche in the TME." (PMID 34502458, 2021). "Equal tumor cell killing capacity of CD4+ and CD8+ CAR-T cells, albeit longer conjunction and delayed kinetics in CD4+ cells, and apoptosis and anergy in CD8+ T cells without the molecular help from CD4+ T cells in the vicinity suggest CD4+ CAR-T can potentiate the effects of the therapy in cancer." (PMID 34012451, 2021).